MGAT5B (alpha-1,6-mannosylglycoprotein 6-beta-N-acetylglucosaminyltransferase B)
Description:
Glycosyltransferase that acts on alpha-linked mannose of N-glycans and O-mannosyl glycans. Catalyzes the transfer of N-acetylglucosamine (GlcNAc) to the beta 1-6 linkage of the mannose residue of GlcNAc-beta1,2-Man-alpha on both the alpha1,3- and alpha1,6-linked mannose arms in the core structure of N-glycan. Also acts on the GlcNAc-beta1,2-Man-alpha1-Ser/Thr moiety, forming a 2,6-branched structure in brain O-mannosyl glycan. Plays an active role in modulating integrin and laminin-dependent adhesion and migration of neuronal cells via its activity in the O-mannosyl glycan pathway.
Synonyms: GNT-Vb; GNT-IX; FLJ25132
Tractability: Antibody: UniProt predicts a signal peptide or a membrane-spanning region. PROTAC: ubiquitination databases record sites on it; its protein half-life has been measured.
Gene: Protein-coding gene on chromosome 17 (76,868,404 to 76,950,393, forward strand). Ensembl gene ENSG00000167889.
Subcellular location: Golgi apparatus membrane
Subcellular location (Human Protein Atlas): Mitotic spindle; Nucleoplasm; Cytokinetic bridge
Pathways (Reactome):
Metabolism of proteins: DAG1 core M2 glycosylations
Gene Ontology:
Molecular function: alpha-1,6-mannosylglycoprotein 6-beta-N-acetylglucosaminyltransferase activity; manganese ion binding; protein binding
Biological process: protein O-linked glycosylation; protein N-linked glycosylation; glycoprotein biosynthetic process
Cellular component: Golgi apparatus; Golgi membrane
Genetic constraint (gnomAD): Loss-of-function variants: 53 observed, 93.15 expected, observed/expected ratio (o/e) 0.57, 90% interval 0.46 to 0.71. The upper end of that interval is the gene's LOEUF score, 0.71, which puts it in group 2 of 6, group 1 being the genes least tolerant of losing a copy. Missense variants: 930 observed, 1,082.6 expected, observed/expected ratio (o/e) 0.86, 90% interval 0.81 to 0.91. Synonymous variants: 460 observed, 450.92 expected, observed/expected ratio (o/e) 1.02, 90% interval 0.94 to 1.1.
Homologues: Orthologues: macaque MGAT5B (98% identical), chimpanzee MGAT5B (97% identical), dog MGAT5B (94% identical), pig MGAT5B (94% identical), guinea pig MGAT5B (92% identical), mouse Mgat5b (91% identical), rat Mgat5b (91% identical), tropical clawed frog mgat5b (73% identical), zebrafish MGAT5B (42% identical), Caenorhabditis elegans gly-2 (29% identical). Paralogues in human: MGAT5 (42% identical), CCDC126 (5% identical).
Diseases named in the same sentence as MGAT5B in open-access papers:
MGAT5B is named in the same sentence as 23 diseases in open-access papers, as found by Europe PMC text mining. Sharing a sentence is not in itself a finding about the gene and the disease. The quoted sentences say what the papers report.
glioblastoma (2 papers, 2021 to 2023). The most malignant astrocytic tumor (WHO grade IV). "Further, Abbott and co-workers reported that knockdown of POMGNT1 and MGAT5B impairs neuronal cell migration, and Lan and co-workers found that silencing of POMGNT1 decreases cell proliferation and invasion in glioblastoma." (PMID 33610554, 2021).
neuroblastoma (2 papers, 2016). Neuroblastoma (NB) is the most common solid, extracranial childhood tumor. "Regarding cancer, MGAT5B was reported to be highly expressed in neuroblastoma cells." (PMID 27136596, 2016).
bladder cancer (1 paper, 2022). "For instance, low expressions of glycosyltransferase genes B4GALT1, EXT1, MGAT5B and POFUT1 predicted poor patient’s survival in bladder cancer." (PMID 36110252, 2022).
cervical cancer (1 paper, 2024). A primary or metastatic malignant neoplasm involving the cervix. "The gene MGAT5B was found to be differentially expressed in Glycan biosynthesis and lipid metabolism processes in cervical cancer cells, regulating the decrease of lipid peroxidation, and the increase in glucose consumption." (PMID 39102232, 2024).
gallbladder tumour (1 paper, 2022).
mastitis (1 paper, 2024). Inflammation of breast tissue during lactation or postpartum due to an obstructed duct or infection. "In dairy cattle milk, MGAT5B was associated with clinical mastitis and SCC." (PMID 39102232, 2024).
mental disorder (1 paper, 2022). A disease that has its basis in the disruption of mental process. "Eight genes are implicated in viral (SEC14L1, JMJD6, SRSF2, TMPRSS2, MX1, MX2) or bacterial (COL8A1, SPIRE1) infections, seven genes (MFSD11, METTL23, CTTNBP2, BACE2, IMPA2, MPPE1 and GNAL) are involved in mental disorders and one gene (MGAT5B) is related to the Golgi complex." (PMID 35581286, 2022).
cancer (8 papers, 2014 to 2024). A tumor composed of atypical neoplastic, often pleomorphic cells that invade other tissues. "In addition, we observed that A549 Hx EVs were enriched in the golgi-expressed glycosylation enzyme alpha 6-mannosylglycoprotein 6-beta-N-acetylglucosaminyltransferase B (MGAT5B) which is a critical regulator of cancer cell–cell contact, EMT, and metastasis." (PMID 33050615, 2020). "Several of these HSEPs have been reported in other contexts to play key roles in tumour progression by cancer cell proliferation (NRSN2, WISP2, SPRX1, LCK), metastasis (GOLM1, STC1, MGAT5B), and stemness (STC1, TMEM59), as well as promoting angiogenesis (ANGPTL4) and host immunosuppression (CD70)." (PMID 33050615, 2020).
tumor (5 papers, 2020 to 2025). "Similarly, MGAT5B is highly correlated with tumor progression and metastasis, and microenvironment hypoxia can further stimulate the expression of MGAT5B." (PMID 34030694, 2021). "The results revealed that hypoxia stimulated cells to synthesize EVs proteins involved in enhancing tumour cell proliferation (NRSN2, WISP2, SPRX1, LCK), metastasis (GOLM1, STC1, MGAT5B), stemness (STC1, TMEM59), angiogenesis (ANGPTL4), and suppressing host immunity (CD70)." (PMID 33050615, 2020).
neurological disorders (2 papers, 2022 to 2025). "However, MGAT5B has also been implicated in neurological disorders, where its deficiency led to decreased astrocyte activation and enhanced oligodendrocyte maturation." (PMID 40790246, 2025). "We suspected that MGAT5B has been subject to negative selection in local chicken populations, resulting in a trade-off that sacrifices some egg yield to potentially reduce the incidence of neurological disorders." (PMID 40790246, 2025). "Indeed, identified genes are implicated in viral (SEC14L1, JMJD6, SRSF2, TMPRSS2, MX1, MX2) bacterial (COL8A1, SPIRE1), and neurological disorders (MFSD11, METTL23, CTTNBP2, BACE2, IMPA2, MPPE1 and GNAL), or in the functions of the Golgi complex (MGAT5B), organelle where viral envelope is occurred." (PMID 35581286, 2022).
MGAT5B also shares sentences with these, for which no sentence is quoted: glioma (4 papers); prostate carcinoma (3); gastric cancer (2); astrocytoma (1); benign prostate hyperplasia (1); breast carcinoma (1); demyelinating disease (1); demyelination (1); endometriosis (1); Hyperglycemia (1); microcephaly (1); oligodendroglioma (1); virus infection (1).